BTLA (B and T lymphocyte associated)
Diseases named in the same sentence as BTLA in open-access papers (continued):
Sharing a sentence is not in itself a finding about the gene and the disease.
cancer (continued). "Additionally, it explores the latest research on BTLA blockade in cancer immunotherapy, offering hope for more effective cancer treatments." (PMID 38233898, 2024). "However, HVEM is expressed not only on cancer cells but also on T cells and can interact with BTLA in cis conformation." (PMID 38835768, 2024). "BTLA is an emerging therapeutic target for immunotherapy in human cancer." (PMID 38928307, 2024). "Moreover, circulating BTLA has been revealed as a blood-based predictive biomarker of immunotherapy response in various cancers." (PMID 37649037, 2023). "On this basis, BTLA/HVEM axis emerges as a novel promising target for cancer immunotherapy." (PMID 37649037, 2023). "Notably, the FCRL family genes demonstrated a significant positive correlation with several immunostimulators, particularly TIGIT, PDCD1, and BTLA, across a range of cancer types." (PMID 37285836, 2023). "A growing body of evidence highlights the important role of BTLA in cancer." (PMID 36741370, 2022). "The BTLA-HVEM pathway has gained recent interest in cancer immunotherapy and autoimmunity." (PMID 35312715, 2022). "Furthermore, in recent years, our research group analyzed the plasma levels of other immunomodulatory proteins, such as BTLA and butyrophilins, in individuals with different cancers." (PMID 36212445, 2022). "In addition to PD-1 and CTLA-4, BTLA is also an immune checkpoint, and is ligated by HVEM to inhibit T cell activation and survival, hence BTLA blockade can enhance cancer immunotherapy." (PMID 36552785, 2022). "Moreover, correlation analysis hinted at a negative correlation of TMEM59L expression with CD8 T cells, activated CD4 T cells, and several immunomodulators, including IDO1, TIGIT, PD-L1, CTLA-4, and BTLA in various cancers." (PMID 36618425, 2022). "Activation of BTLA suppressed the function of CD8 cancer-specific T cells." (PMID 36090045, 2022). "Altogether, these data suggest that BTLA is transcribed by cancer cells." (PMID 36552785, 2022). "To test this hypothesis, we further validated the results by immunoblot analysis in the BTLA KD and KO cancer cells." (PMID 36552785, 2022). "Also, studies of other groups of the Chinese population showed a correlation between BTLA SNPs and cancer development." (PMID 36741370, 2022). "Overall, these data demonstrate that BTLA is expressed in a subpopulation of cancer cells." (PMID 36552785, 2022). "Therefore, we analyzed BTLA transcription in the Cancer Cell Line Encyclopedia (CCLE) with pure cancer cell lines, which revealed that BTLA was transcribed in cancer cell lines." (PMID 36552785, 2022). "To identify potential therapeutic targets of those cancers and immune escape, we have collected more than forty representative immune checkpoint genes, including BTLA, CD200, TNFRSF14, NRP1, LAIR1 and so on, and we evaluated the relationship between expression of COL1A1 and immune checkpoint." (PMID 35789341, 2022). "However, in a similar manner to sPD-1 experiments, blockade of BTLA-HVEM with sBTLA have shown enhanced anti-cancer immunity in in vitro and in vivo studies." (PMID 34531847, 2021). "Lastly, our research revealed a markedly close interaction between BTLA and anti-cancer immunity." (PMID 33718105, 2020). "Besides, the correlations between BTLA and cancer immune infiltration were investigated via CIBERSORT." (PMID 32793631, 2020). "We first screened and compared the expression of BTLA in different cancer types." (PMID 32793631, 2020). "The present study provides insight into the role of the BTLA in anti-cancer immunity that may lead to the development of BTLA targeting therapy to assess the efficacy and receptiveness in SKCM treatment." (PMID 33718105, 2020). "BTLA blockade also bolsters the stimulatory effects of PD‐1 blockade on alloreactive CD8+ T cells, suggesting that combinatorial interference with BTLA and PD‐1 could be a useful approach for augmenting antitumor T cell responses in cancer patients." (PMID 32508018, 2020).
cancer (continued). "We evaluated the expression of BTLA via the Oncomine and the cancer genome atlas (TCGA) database." (PMID 32793631, 2020). "Gene BTLA is identified as important for eight cancer types with B2." (PMID 31405076, 2019). "The activation of BTLA leads to inhibition of CD8+ cancer-specific T-cells." (PMID 31929796, 2019). "Collectively, these studies suggest that the soluble form of the BTLA protein present in serum may serve as a prognostic factor of disease progression and as a predictive marker in response to treatment in some types of cancer." (PMID 38233898, 2024). "BTLA may be a novel therapeutic target for cancer immunotherapy." (PMID 34163466, 2021). "Therefore, the combination of chemotherapy and anti-BTLA Ab for treating cancer may hold clinical potential." (PMID 31753019, 2019). "An increased expression of BTLA and its ligand HVEM has been shown in cancer and, particularly, in B-cell lymphoproliferations, including CLL." (PMID 40647414, 2025). "Results of the current study showed an increased BTLA, CD96 and PD1 expression in cancer tissue samples and a significant positive correlation of BTLA and PD1 expression to the immune checkpoint CD96." (PMID 38928307, 2024). "In contrast, no clinical evidence is available for anti-LAG3, anti-TIGIT, anti-BTLA, anti-ICOS and anti-IDO1 antibodies in MSI-H cancers, but clinical trials are ongoing." (PMID 38254772, 2024). "Exhausted T cells in cancer express high levels of inhibitory receptors, including PD-1, CTLA-4, TIM-3, LAG3, BTLA, and TIGIT, most of which are also known as Treg markers." (PMID 36901957, 2023). "Several inhibitory immunoreceptors have been discovered and studied in cancers, and apart from PD-1 also include CTLA-4, LAG3, TIM3, TIGIT, BTLA, etc." (PMID 38067344, 2023). "In the context of cancer, the immunoregulatory function of HVEM and its ligands, especially BTLA due to its inhibitory nature, is altered, hence contributing to the dysregulation of antitumor immunity." (PMID 37649037, 2023). "This review thoroughly dissects current molecular and functional knowledge of BTLA/HVEM axis and the future perspectives to become a target for cancer immunotherapy." (PMID 37649037, 2023). "Concerning immune checkpoints, highly expressed TNFSF14 in Neutrophils, NK Cells, and Monocytes, BTLA in Treg Cells, Granulosa Cells, and B Cells, together with LTBR and TNFRSF14 in Cancer Cells, interact to help kill Cancer Cells." (PMID 36401283, 2022). "Other potential immune checkpoints, such as LAG3, CD96, PDCD1, BTLA, IDO1, and TIGIT, were also enriched in PTPRD/PTPRT mutant cancers." (PMID 36248841, 2022). "al recently assessed the association between sBTLA and BTLA cell expression in a small number of cancer patients, and found a strong correlation between serum levels of sBTLA and the percentage of peripheral CD8+T cells expressing BTLA." (PMID 35312715, 2022). "Other immunoreceptors extensively studied in cancer are LAG-3, TIGIT, T-cell immunoglobulin and mucin containing protein-3 (TIM3) and B and T lymphocyte attenuator (BTLA)." (PMID 35211124, 2022). "Also, the explanation of a lack of BTLA SNPs effect on smokers might lay in such a strong contribution of smoking to cancer risk that a relatively weak effect of rs1982809 disappeared." (PMID 36741370, 2022). "Significantly higher median serum levels of BTLA, CD27 and CD80 proteins were found in the group of high-grade carcinomas compared to the group of low-grade carcinomas (p = 0.01, p = 0.01, p = 0.03, respectively)." (PMID 35204342, 2022). "We found that in some cancers, especially in LUAD and TGCT, FH expression was significantly correlated with multiple immune checkpoint markers, such as BTLA, TNFRSF14, LAIR1, CD48, and CD28." (PMID 34737838, 2021). "A soluble form of BTLA and HVEM can be detected in the sera of healthy individuals and cancer patients." (PMID 34531847, 2021).
cancer (continued). "The immune checkpoint B- and T-lymphocyte attenuator (BTLA/CD272) and its ligand, Herpesvirus entry mediator (HVEM/CD270/TNFRSF14), are dysregulated in cancer." (PMID 33917094, 2021). "Our recent study showed that in contrast to other types of cancer, BTLA protein level is significantly decreased in CLL B cells compared to normal lymphocytes, despite high expression of BTLA mRNA in CLL." (PMID 34831232, 2021). "Our studies are focused on BTLA/HVEM complex, which inhibits T-cell proliferation and cytokine production and therefore has great potential as a new target for cancer treatment." (PMID 33238640, 2020). "Future research is required to explore the elaborate mechanism of BTLA in CRC and investigate the functions of BTLA in other cancers." (PMID 32793631, 2020). "Our findings provide a novel understanding of cancer biology in SKCM and found that immune-related signal pathways were significantly correlated with BTLA." (PMID 33718105, 2020). "In a single SNP analysis, the BTLA rs2171513 G>A genotype frequencies were 62.83% (GG), 32.67% (GA) and 4.50% (AA) in EGJA patients and 63.70% (GG), 32.27% (GA) and 4.03% (AA) in the cancer-free controls." (PMID 31774112, 2019). "In this study, we evaluated the potential of BTLA to predict outcomes for EOC patients clinically and as targets for cancer treatment preclinically." (PMID 31753019, 2019). "Exploring the underlying mechanism of the distinctive expression pattern of BTLA and HVEM in different T cell subsets is an important future goal for designing more effective cancer immunotherapy." (PMID 30116751, 2018). "Regarding receptors, there exhibited a strong correlation with PD-1 and receptors including TIGIT, CTLA-4, LAG3, BTLA, ICOS, TNFRSF9, CD27 in most types of cancer." (PMID 30607140, 2018). "Our studies extend the current understanding about a distinct coinhibitory molecule expression pattern in CD4+ and CD8+ T cells, by showing distinct changes of BTLA and HVEM expressions on CD4+ and CD8+ T cell subset in human cancers." (PMID 30116751, 2018). "It is known that BTLA is involved in the negative regulation of T-cell responses by interacting with HVEM, highlighting BTLA as a potential target for cancer immunotherapy." (PMID 28594868, 2017). "Thus, blockade of BTLA might have potential in cancer therapy." (PMID 28588576, 2017). "While all were able to survive the infection, at day 14, endogenous CD4+ and CD8+ T cell compartments in cancer mice continued to contain higher frequencies of CD4+PD-1+BTLA+ and CD8+BTLA+ T cells." (PMID 24796533, 2014). "This review provides a comprehensive overview of the regulation and therapeutic targeting of immune checkpoint proteins in cancer, covering both classical checkpoints, including PD-1, PD-L1, and CTLA-4, and emerging targets such as LAG-3, TIM-3, TIGIT, BTLA, SIRP-α, CD200, ILT4, and CD24." (PMID 42279386, 2026). "Taken together, these observations highlight a consistent theme across cancer types: high BTLA expression is not merely a marker of immune suppression but also a feature linked to biologically aggressive tumors." (PMID 41471273, 2025). "At the single‐cell level in non‐responders, nearly all immuno‐suppressive/exhausted markers as PD‐1, CTLA4, and BTLA, along with CCR6, a receptor comprising CCR6/CCL20 axis and promoting cancer progression, elevated consistently in peripheral HLA‐DR+CD8+ T cells." (PMID 39467150, 2024). "Researchers have found a number of immune checkpoint signals in cancers that could confer strong immunosuppression on cancer cells by combining ligands with inhibitory immunoreceptors, such as PD-1, TIGIT, CTLA-4, BTLA, LAG3, and TIM3." (PMID 36895440, 2023). "Since BTLA and HVEM were expressed in a subpopulation of cancer cells, we hypothesized that cell growth may further be inhibited by the simultaneous overexpression of BTLA and HVEM." (PMID 36552785, 2022).
cancer (continued). "As previously reported, in the cancer-immunity cycle, CD28: (CD80, CD86), CD40, CD27, HVEM, GITR: GITRL, ICOS, and TLR-2 are stimulatory factors, while TIM-3, PD-L1: PD-1, PD-L1: (CD80, CD86), CTLA-4: (CD80, CD86), BTLA, and LAG-3 are inhibitory factors." (PMID 35419462, 2022). "The expression of BTLA and its ligand HVEM has been documented to be deregulated in cancer." (PMID 36741370, 2022). "BTLA and HVEM were also expressed in clinical cancer samples, supporting our findings." (PMID 36552785, 2022). "Similarly, other checkpoints, including TIM-3, BTLA, and LAG-3, are under active investigation as potential biomarkers for cancer theranostics." (PMID 34940257, 2021). "Also of notice, a pronounced number of critical immunomodulators, which were described in an immunogenomic analysis of major TCGA cancer data sets and included PDCD1LG2, BTN3A2, GZMA, BTLA, CD28, ICOS, and IDO1, were contained in the 358 DEG set." (PMID 32603365, 2020). "To comprehensively investigate the immunoinhibitory pathways in T cells, we used FACS to analyze the surface expression of eight IRs (PD-1, Tim-3, BTLA, KLRG-1, TIGIT, 2B4, CD160, and CTLA-4) on T cells from peripheral blood and tumors isolated from 131 cancer patients." (PMID 31709176, 2019). "Compared to mice without cancer, mice with cancer possessed increased frequencies and absolute numbers of 2B4+, BTLA+, and PD-1+ T cells." (PMID 29338031, 2018). "The distinct changes of BTLA and HVEM on circulating CD4+ and CD8+ T cells could be taken into consideration when targeting BTLA or HVEM in cancer immunotherapy." (PMID 30116751, 2018). "Specifically, in the cancer group, bacterial antigen-specific CD8+ T cells showed increased BTLA expression; PD-1 and 2B4 expression trended higher in the cancer group but was not significant." (PMID 24796533, 2014). "Similarly, the endogenous CD8+ T cell population in the cancer group also exhibited increased expression of CD8+BTLA+ and CD8+PD-1+BTLA+ T cells at day 5 post-infection." (PMID 24796533, 2014). "Another protein involved in the inhibition of the immune response against cancer cells, HVEM (herpesvirus entry mediator), was the target of a study in which linear and cyclic peptides were designed as antagonists of its interaction with BTLA (B- and T-lymphocyte attenuator)." (PMID 38339078, 2024). "Thus, the regulation of HVEM, BTLA, LIGHT, and CD160 expression on immune cells plays a pivotal role in determining the degree of immune activation or inhibition, significantly influencing the immune response to cancer." (PMID 39684559, 2024). "Hence, BTLA/HVEM axis emerges as a novel and promising target for cancer immunotherapy." (PMID 37649037, 2023). "BTLA/HVEM axis dysregulation has been linked to poor outcome and diminished antitumor immune responses in a wide variety of cancers, including solid tumors (e.g. pancreatic adenocarcinoma, non-small-cell lung cancer) and those from the hematological origin (e.g. follicular lymphoma, CLL)." (PMID 37041226, 2023). "Although BTLA and PDL1 employ distinct phosphatases to suppress T-cell signaling, both of them dampen the TCR and CD28 signaling pathways equally, and thus the inhibitors of both BTLA and PDL1 might be regarded as a combination of immunotherapeutic agents for cancer treatment." (PMID 35127742, 2021). "LncRNA TSPOAP1-AS1 showed a significant correlation with the immune-related gene BTLA in 15 kinds of cancers, with a strong correlation in PAAD and CHOL (|r| > 0.8), and the other mainly significant immune genes included CD28 (in 18 types of cancer) and CD40LG (in 14 types of cancer)." (PMID 34195204, 2021). "In addition, we found that blockade of BTLA signaling increased IFN-γ production in both circulating CD4+ and CD8+ T cells isolated from HCC patients, which strengthens the emerging notion that BTLA can be used as a target of cancer immunotherapy." (PMID 30116751, 2018).
cancer (continued). "Moreover, BTLA and Cbl-b were exclusively expressed on TI immune cells and not on cancer cells." (PMID 38233898, 2024). "However, there are many other proteins, such as lymphocyte activation gene-3 (LAG-3, CD223), B and T cell lymphocyte attenuator (BTLA, CD272), T cell immunoglobulin-3 (TIM-3), etc., which play important roles in the immune response to cancer, although their mechanisms of action remain unclear." (PMID 32018226, 2020). "The study found a negative correlation among STAAD cancer patients between NPRL2 expression and PDCD1LG2, LAIR1, and BTLA checkpoint markers." (PMID 39932765, 2025). "Analysis of co-expression of two and more exhaustion markers shows that combination of BTLA and CD160 with or without LAG-3, conversely to other markers, show the maximum of downregulation in cancer samples." (PMID 39234236, 2024).